IL16 (interleukin 16)
Diseases named in the same sentence as IL16 in open-access papers (continued):
Sharing a sentence is not in itself a finding about the gene and the disease.
multiple sclerosis (5 papers, 2006 to 2021). A progressive autoimmune disorder affecting the central nervous system resulting in demyelination. "IL-16 may be implicated in some neurodegenerative diseases such as multiple sclerosis (MS) where enhancement of IL-16 production suggests a role in the regulation of inflammation in axonal damages." (PMID 23878582, 2013). "Interleukin-16 is a protein involved in the migration of some immune cells and plays an important role in the development of multiple sclerosis, an inflammatory demyelinating disease that affects the central nervous system (i.e., brain and spinal cord)." (PMID 34071825, 2021). "Our findings suggest that interleukin-16 is closely involved in the pathology of multiple sclerosis and other inflammatory diseases in the central nervous system via the glial and infiltrating immune cells." (PMID 34071825, 2021). "This study investigates the correlation between the expression levels of interleukin-16 and the severity of neuroinflammation and determines the cells which produce interleukin-16, using a mouse model of multiple sclerosis." (PMID 34071825, 2021).
periodontitis (5 papers, 2014 to 2025). An acute or chronic inflammatory process that affects the tissues that surround and support the teeth. "Several polymorphism studies in periodontitis including matrix metalloproteinase 3, interleukin 16 (IL-16), IL1α, and tumor necrosis factor α (TNFα) have been carried out." (PMID 38169768, 2023). "Environmental factors that alter the immunopathogenesis of periodontitis, such as smoking, influenced the association of IL16 with PD." (PMID 32915917, 2020). "Thus, the IL16 rs16556218 polymorphism and the serum levels of IL-16 were associated with periodontitis in a Brazilian sample, and this was influenced by environmental factors such as smoking." (PMID 32915917, 2020). "Distribution of genotype and allele frequencies for IL16 polymorphisms in the periodontitis (PD) patients compared to controls (smokers plus nonsmokers’ individuals)." (PMID 32915917, 2020). "The IL16 rs11556218 polymorphism and the IL-16 serum level were associated with protection for periodontitis in a nonsmoking Brazilians sample, although they seem to be independent events." (PMID 32915917, 2020). "We identified the CHEMERIN, HGF, IFN-I, IL16, LIFR, and APELIN pathways as not being active during homeostasis but rather, to be active in periodontitis." (PMID 36193890, 2022).
preeclampsia (5 papers, 2015 to 2025). Preeclampsia is a hypertensive disorder of pregnancy that is characterized by new-onset hypertension with proteinuria presenting after 20 weeks of gestation, and depending on mild or severe forms may initially present with severe headache, visual disturbances, and hyperreflexia. "This review emphasizes the substantial contribution of interleukins IL-15, IL-16, IL-17, and IL-35 to the immunopathology of preeclampsia." (PMID 41375625, 2025). "In preeclampsia, hsa_circ_0001326 increases IL16 expression to regulate proliferation, migration, invasion, and EMT." (PMID 36176289, 2022). "The aim of our study was to analyse the potential role of sFlt1, PlGF, sEng, IL-6, and IL-16 in predicting PE and eventually to find a practical panel of biomarkers useful in early diagnosis of preeclampsia." (PMID 27799724, 2016). "Serum levels of pro-inflammatory IL-15 and IL-16 are significantly higher in preeclampsia than in normal pregnancy." (PMID 26247971, 2015).
sarcopenia (5 papers, 2022 to 2025). Progressive decline in muscle mass due to aging which results in decreased functional capacity of muscles. "We also measured the expression of a novel cytokine that has recently been linked to cancer and sarcopenia, IL‐16." (PMID 41267538, 2025). "Twenty‐seven factors were causally related to sarcopenia and aging traits, and the causal effects of IL16, CTACK, MIP1b and PDGFbb were proven in both analyses with two significance thresholds." (PMID 38556722, 2024). "In summary, IL16 had the largest number of causal associations with sarcopenia and aging traits, but the results were still paradoxical." (PMID 38556722, 2024). "Studies have found that women with sarcopenia have higher IL-16 levels than controls, whereas men have lower levels, suggesting that chronic inflammation can cause sarcopenia." (PMID 37892780, 2023). "Because the sex-specific risk factors for sarcopenia were the focus of this study, we systematically calculated the share of sarcopenia patients (percentage) via increasing variables, serum IL-16 levels, and MNA scores." (PMID 37630720, 2023). "In male older adults, however, malnutrition (p = 0.028) and low serum levels of IL-16 (p = 0.031) were the most significant risk factors for sarcopenia." (PMID 37630720, 2023). "This study is the first to examine and report the association of sarcopenia with IL-16 levels in GC cases, as well as their integrated relation with GC survival." (PMID 35215488, 2022). "In the results of MR analyses, the causal roles of IL16 in different sarcopenia traits were controversial: IL16 may have positive effects on hand grip strength and AWCU10 while having negative effects on AALM and MVPA." (PMID 38556722, 2024). "Previous population studies have reported that IL16 has a sex‐specific association with sarcopenia: IL16 may be a protective factor for males and a risk factor for females." (PMID 38556722, 2024). "While nutritional deficiency may directly contribute to sarcopenia in males, the impact of IL-16 appears to be more relevant in female muscle generation." (PMID 37630720, 2023). "Moreover, a high IL-16 serum level ≥150 pg/mL was the most significant risk factor for sarcopenia in older females (OR: 9.53, 95% CI: 1.09, 83.44, p = 0.029)." (PMID 37630720, 2023). "Moreover, the impact of IL-16 on sarcopenia underlies sex differences; therefore, the serum IL-16 level may serve as a potential biomarker for sarcopenia in older women." (PMID 37630720, 2023). "In the expression analyses of muscle tissues, the patients with sarcopenia also have higher levels of IL16 expression." (PMID 38556722, 2024). "IL16, CTACK, MIP1b and PDGFbb were proven to relate to at least one sarcopenia and aging trait causally in both Analyses A and B. Reserve MR analyses also proved their unidirectional causal effects." (PMID 38556722, 2024). "In females, the OR for sarcopenia was more than ninefold higher with IL-16 serum levels over 150 pg/mL (OR: 9.52, 95% CI: 1.09, 83.44, p = 0.029)." (PMID 37630720, 2023). "In sharp contrast to the male participants, almost 90% of the females with sarcopenia had elevated IL-16 serum levels." (PMID 37630720, 2023). "In contrast, males with sarcopenia had lower IL-16 (p = 0.013) levels than males in a control group." (PMID 37630720, 2023). "Most importantly, the data indicate discordant risks for sarcopenia in males and females with IL-16 serum levels higher than 150 pg/mL (OR: 9.53, 95% CI: 1.09, 83.44, p = 0.029)." (PMID 37630720, 2023). "The presence of sarcopenia accompanied by the inflammatory factor IL-16 remarkably indicates a dismal prognosis." (PMID 35215488, 2022). "When sarcopenia was accompanied by high IL-16 expression and GC survival stratified by age, sex, body mass index, and pTNM stage, they had markedly impaired survival stratified by age, sex, BMI, and pTNM stage." (PMID 35215488, 2022).
sarcopenia (continued). "Because the nature of our study is retrospective, we cannot obtain the blood plasma of patients to further study the relationship between serum levels of IL-16 and sarcopenia." (PMID 35215488, 2022). "Later, we grouped the patients with sarcopenia and IL-16 expression and discovered that the patients with sarcopenia and IL-16 upregulation displayed the poorest OS (HR = 3.02; 95% CI = 1.64–5.91) and RFS (HR = 2.34; 95% CI = 1.47–4.69)." (PMID 35215488, 2022). "There were more cases showing high IL-16 expression detected in the sarcopenia group (55.7% vs. 37.3%, p = 0.003)." (PMID 35215488, 2022). "As shown in the Kaplan–Meier curves, sarcopenia cases showing IL-16 upregulation displayed the poorest prognosis, while patients without sarcopenia and IL-16 downregulation displayed the most favorable survival (p < 0.001 upon log-rank test)." (PMID 35215488, 2022). "In conclusion, the present work is the first to investigate the close relationship of sarcopenia with IL-16 in GC." (PMID 35215488, 2022). "Sarcopenia accompanied by high IL-16 expression remarkably indicates a dismal prognosis in GC patients." (PMID 35215488, 2022). "The effects of IL16 on sarcopenia need more experimental evidence." (PMID 38556722, 2024). "Overall, our study presents a novel hypothesis regarding the sex-specific pathogenesis of sarcopenia in older adults and proposes the potential use of IL-16 as a specific marker for the development of sarcopenic obesity in older women." (PMID 37630720, 2023). "Furthermore, the data highlight a possible involvement of IL-16 in the sex-specific pathogenesis of sarcopenia in older adults." (PMID 37630720, 2023). "However, both Fisher’s exact test and the 3D probability model identified a high IL-16 level as a protective factor against sarcopenia in males, yielding statistically significant results (OR: 0.18, 95% CI: 0.04, 0.81, p = 0.031)." (PMID 37630720, 2023). "Moreover, women with sarcopenia exhibited significantly higher IL-16 (p = 0.025) serum levels than women in a control group." (PMID 37630720, 2023). "Taken together, IL-16 serum levels may serve as an indicative marker for sarcopenia in male and female adults differentially." (PMID 37630720, 2023). "Based on our results, higher IL-16 expression was detected in GC patients with sarcopenia." (PMID 35215488, 2022). "In conclusion, more IL-16 upregulation was noted in GC patients with sarcopenia." (PMID 35215488, 2022). "The sarcopenia group had more cases showing IL-16 upregulation (55.7% vs. 37.3%, p = 0.003)." (PMID 35215488, 2022). "Sarcopenia and high IL-16 expression predicted the dismal prognosis of GC cases." (PMID 35215488, 2022). "The combination of IL-16 expression and sarcopenia may be able to identify patients with GC with a poor prognosis." (PMID 35215488, 2022). "Sarcopenia and high IL-16 expression were identified as independent factors to predict OS (hazard ratios [HR] = 1.64 and 1.79, 95% confidence interval [CI] = 1.25–2.23 and 1.16–2.78, respectively) and RFS (HR = 1.43 and 1.60, 95% CI = 1.15–2.95 and 1.10–2.37, respectively)." (PMID 35215488, 2022). "Later, we combined sarcopenia with IL-16 levels to analyze their relationship with prognosis." (PMID 35215488, 2022). "However, little evidence from cellular and molecular levels was reported, and the precise mechanisms by which IL16 contributes to the development of sarcopenia remain unclear." (PMID 38556722, 2024). "The causal effects of IL16, CTACK, MIP1b and PDGFbb were proven in both analyses with two significance thresholds, which suggested that these four factors may have the most significant causal effects on sarcopenia and aging traits." (PMID 38556722, 2024). "IL16 (interleukin‐16), CTACK (cutaneous T‐cell attracting chemokine), MIP1b (macrophage inflammatory protein 1b) and PDGFbb (platelet‐derived growth factor BB) were proven to relate causally to at least one sarcopenia and aging trait in both analyses with two significance thresholds." (PMID 38556722, 2024).
sarcopenia (continued). "Based on the disparities observed in IL-16 levels and BFRs between the male and female sarcopenic patients in the patient and control groups, as well as the subsequent discussion on sarcopenic obesity in females, our study suggests a sex-specific variation in the pathogenesis of sarcopenia." (PMID 37630720, 2023). "Thus, the present work explored the relationship of sarcopenia and IL-16 with GC patient survival." (PMID 35215488, 2022). "However, the association of sarcopenia with IL-16 among GC cases has not been investigated thus far." (PMID 35215488, 2022). "Therefore, we have to consider that IL16 may have different effects on sarcopenia traits." (PMID 38556722, 2024). "Thus, it is conceivable that IL-16 may lead to sarcopenia by changing female hormone levels." (PMID 37630720, 2023). "Six cytokines and growth factors were identified to relate to the sarcopenia traits and telomere length: CTACK (cutaneous T‐cell attracting chemokine), eotaxin, IL16 (interleukin‐16), IL18 (interleukin‐18), MIP1b (macrophage inflammatory protein 1b) and PDGFbb (platelet‐derived growth factor BB)." (PMID 38556722, 2024). "We found a significant negative correlation between the IL-16 level and ASMI in females (r = −0.342, p = 0.021) and identified elevated serum IL-16 as a risk factor for sarcopenia in females (OR: 9.53, 95% CI: 1.09, 83.44, p = 0.029)." (PMID 37630720, 2023).
Stroke (5 papers, 2010 to 2026). Sudden impairment of blood flow to a part of the brain due to occlusion or rupture of an artery to the brain. "The chemo-attractant protein IL-16 and cathepsin enzyme inhibitor CSTB were the only proteins found elevated in patients with improved stroke volume." (PMID 33122738, 2020). "There was locally enhanced expression of iNOS, IL-16, IL-1ß and TNF-α in smooth muscle cells in the ischemic region both in the MCA leading to the stroke region and in microvasculature walls." (PMID 20187933, 2010). "Measuring 65 plasma cytokines and chemokines revealed that individuals with stroke due to LAA, CE, and SVO have a stronger inflammatory response than those with sCeAD, particularly for the analytes HGF, SDF-1α, IL-2R, CD30, TNF-RII, IL-16, MIF, APRIL, and SCF." (PMID 38802464, 2024).
systemic sclerosis (5 papers, 2020 to 2025). A chronic disorder, possibly autoimmune, marked by excessive production of collagen which results in hardening and thickening of body tissues. "Interestingly, other investigators described that in the skin affected by systemic sclerosis, approximately 1/3 of the infiltrating cells express IL-16." (PMID 33931094, 2021). "The regulatory role of IL-16 in the inflammation involved in other systemic diseases has been widely reported, including systemic sclerosis, gouty inflammation, and MRSA pneumonia and lung injury, while its role in cardiac inflammation has been discussed less often." (PMID 33958974, 2021).
Thrombocytopenia (5 papers, 2019 to 2022). A reduction in the number of circulating thrombocytes. "The CRS was evidenced by raised inflammatory markers, thrombocytopenia, elevated cytokine levels (IFN-γ/IL-2R/IL-18/IL-16/IL-10) and steroid responsiveness." (PMID 34040262, 2021). "In contrast, PedSep-D had the most profound inflammatory response with highest M-CSF, IL-8, SCF, sCD163, IL-16, IL-10, TNF, and MIP1α levels, and thrombotic microangiopathic response with lowest ADAMTS13 activity decreased to < 57% of control with thrombocytopenia." (PMID 35526000, 2022). "Au and colleagues presented a patient with fever, thrombocytopenia, CRP increase and elevation of several cytokines including interferon-γ, sIL-2R, IL-18, IL-16 and IL-10 after vaccination and ICI therapy compared to cytokine levels before initiation of ICI therapy and vaccination." (PMID 35715501, 2022).
Autoimmunity (4 papers, 2006 to 2025). The occurrence of an immune reaction against the organism's own cells or tissues. "The data presented here suggest that IL-16 and MIF are neutrophil-derived inflammatory mediators released under conditions of insufficient clearance of apoptotic neutrophils, as typically occurs at sites of infection and autoimmunity." (PMID 27551482, 2015). "Due to the fact that late-differentiated memory CD4+ T cells very often showed crossreactivity 27, alloreactivity 28 and autoreactivity 29–31, the lack of IL-16 and Treg lymphocytes may lead to enhanced inflammation and eventually promotion of autoimmunity." (PMID 26029366, 2015).
HIV-1 infection (4 papers, 2020 to 2025). The type species of lentivirus and the etiologic agent of acquired immunodeficiency syndrome (AIDS). "Cells overexpressing IL-16 are resistant to HIV-1 infection, and IL-16 has been explored as a co-enhancer of HIV-1 virus eradication." (PMID 40529362, 2025). "Given that CD4 acts as a receptor for IL16 in T cells the function of IL16 on infectious diseases has mainly been investigated in HIV-1 infection." (PMID 34630361, 2021). "Given the association of IL16 with CD4 that is a primary cellular receptor for HIV-1 entry, the role of IL16 in HIV-1 infection has been extensively studied." (PMID 32735617, 2020). "To further enhance the safety and efficacy of HSC-based CAR therapy, here we tested a novel, truncated D1D2CAR designed to eliminate IL-16 mediated signaling and CD4CAR mediated HIV-1 infection." (PMID 33793675, 2021). "IL16 can repress HIV-1 promoter activity and viral transcription, providing a therapeutic value in HIV-1 infection." (PMID 32735617, 2020). "We found that D1D2CAR did not mediate HIV-1 infection, did not react to IL-16 stimulation and had similar anti-HIV-1 activity as compared to CD4CAR both in vitro and in vivo." (PMID 33793675, 2021). "When IL16 was added before HIV-1 infection, it could repress HIV-1 LTR expression in lymphoid but not monocytoid cells." (PMID 34630361, 2021).
knee osteoarthritis (4 papers, 2015 to 2020). "This study investigates the association between IL-16 polymorphisms and the risk of knee osteoarthritis (OA) in a Chinese population." (PMID 25954818, 2015). "With regard to diseases with alteration of bone homeostasis, the protective effects of this polymorphism were observed in knee osteoarthritis, which may be the result of changes in IL-16 activity altering the effects of chronic inflammation on the synovial membrane." (PMID 32915917, 2020). "The correct title is: Correlation of serum cartilage oligomeric matrix protein (COMP) and interleukin-16 (IL-16) levels with disease severity in primary knee osteoarthritis: A pilot study in a Malaysian population." (PMID 29281738, 2017). "The aim of this study was to investigate the correlations between serum cartilage oligomeric matrix protein (COMP), interleukin-16 (IL-16) and different grades of knee osteoarthritis (KOA) in Malaysian subjects." (PMID 28910372, 2017). "The correct citation is: Das Gupta E, Ng WR, Wong SF, Bhurhanudeen AK, Yeap SS (2017) Correlation of serum cartilage oligomeric matrix protein (COMP) and interleukin-16 (IL-16) levels with disease severity in primary knee osteoarthritis: A pilot study in a Malaysian population." (PMID 29281738, 2017).
osteosarcoma (4 papers, 2016 to 2024). A usually aggressive malignant bone-forming mesenchymal neoplasm, predominantly affecting adolescents and young adults. "Higher IL-16 levels, as a functional consequence of rs11556218 TG/GG genotypes, were confirmed in patients with osteosarcoma, nasopharyngeal carcinoma, and benign conditions like osteoporosis." (PMID 39408600, 2024). "In patients with osteosarcoma, IL16 variants were related to higher levels of IL-16 and, consequently, in the effects in the production of other tumor-related inflammatory cytokines, such as TNF-α and IL-1β." (PMID 32915917, 2020).